BRD4 (bromodomain containing 4)
Diseases named in the same sentence as BRD4 in open-access papers (continued):
Sharing a sentence is not in itself a finding about the gene and the disease.
ischemia (5 papers, 2017 to 2024). A hypoperfusion of the BLOOD through an organ or tissue caused by a PATHOLOGIC CONSTRICTION or obstruction of its BLOOD VESSELS, or an absence of BLOOD CIRCULATION. "We delved into the underlying mechanisms of protection by dBET1 by investigating the effects of BRD4 blockade on ischemia-induced inflammation and oxidative stress." (PMID 35761277, 2022). "Pretreatment of rats with the selective Brd4 inhibitor NHWD-870 before the onset of ischemia considerably reduced kidney damage severity and restored nearly normal renal tissue architecture compared to renal injury severity in both the control and vehicle groups." (PMID 37675155, 2023). "This investigation revealed that pretreatment with the selective Brd4 inhibitor JQ1 prior to the onset of ischemia could considerably lessen the severity of kidney injury compared to the severity of renal injury in the control and vehicle groups." (PMID 37520478, 2023). "This experimental study demonstrated that pretreatment with the BRD4 selective inhibitor JQ1 prior to the induction of ischemia might dramatically reduce the level of inflammatory cytokines (TNF) compared to those in the control and vehicle groups." (PMID 37520478, 2023). "Recent structural and chemical analyses of BRD4 and its inhibition studies indicate a critical role of BRD4 in coordinating inflammatory and oxidative processes in response to different insults, including ischemia." (PMID 35761277, 2022). "Moreover, these authors demonstrated that the BRD4 expression in the renal tissue is not modified after ischemia, in accordance with our results where the BRD4 protein levels remained unchanged, both in vitro and in vivo, following UPR pathway activation." (PMID 38481808, 2024).
lymph node metastasis (5 papers, 2016 to 2022). "Consistently, we found that BRD4 was upregulated in the OSCC specimens from cases with lymph node metastasis." (PMID 32499570, 2020). "Univariate analysis demonstrated that BRD4 expression (p < 0.001), lymph node metastasis (p < 0.001), lymphatic permeation (p < 0.001), and TNM stage (p < 0.001) were significant prognostic factors for poor survival." (PMID 28415703, 2017). "Clinically, we observed that the BRD4 level was significantly related to histological type, lymph node metastasis, tumor stage and differentiation." (PMID 26840017, 2016). "Furthermore, BRD4 was highly expressed in OSCC patients with lymph node metastasis, including patients who exhibited metastasis after the initial diagnosis." (PMID 32499570, 2020). "Analyses of biopsy specimens from OSCC patients revealed that the BRD4 and MMP2 expression levels were correlated in the cancerous regions, and both were highly expressed in lymph node metastasis cases, including delayed metastasis." (PMID 32499570, 2020). "Furthermore, both BRD4 and MMP2 were highly expressed, not only in the cancerous tissues of patients with lymph node metastasis (N(+)) but also in cases with delayed metastasis (N(d.m.))." (PMID 32499570, 2020). "To explore the role of BRD4 in OSCC metastasis, we classified the patients into groups with and without lymph node metastasis at the time of the initial diagnosis and treatment." (PMID 32499570, 2020).
mantle cell lymphoma (5 papers, 2020 to 2023). Mantle cell lymphoma is a rare form of malignant non-Hodgkin lymphoma affecting B lymphocytes in the lymph nodes in a region called the ``mantle zone''. "We recently introduced thienopyranone (TP) scaffold-based chemotypes for the combinatorial inhibition of BTK, PI3K-AKT, and BRD4-MYC in a single compound (i.e., SRX3262 and SRX3305) and demonstrate impressive preclinical activity in mantle cell lymphoma (MCL)." (PMID 35743155, 2022). "In mantle cell lymphoma (MCL), SEs regulate genes related to cell survival through BRD4, such as B cell receptor (BCR) signaling and IKZF-MYC axis, and the inhibition of BRD4 may overcome MCL resistance to ibrutinib (BCR pathway inhibitor) or lenalidomide (IKZF inhibitor)." (PMID 34011395, 2021).
myelofibrosis (5 papers, 2022 to 2025). A partial or complete replacement of the bone marrow stroma by fibrous tissue. "CPI-0610 demonstrates superior pharmacological properties compared to JQ1, an earlier BRD4 inhibitor and is currently undergoing clinical development with a manageable safety profile for hematologic malignancies, particularly myelofibrosis." (PMID 40809038, 2025). "Interestingly, fedratinib, a selective oral JAK2 inhibitor recently approved in the United States for treatment of adult patients with myelofibrosis, which has off-target activity against the VIPs BRD4, TBK1, MARK1 and CSNK2A2, also displayed a similar proviral effect in our disease system." (PMID 36305426, 2022). "This compound is an experimental myelofibrosis and cancer drug (clinicaltrials.gov, NCT04454658, accessed July 21, 2023) that acts as an inhibitor of BET bromodomain proteins, specifically BD2 domain of BRD2, BRD3 and BRD4." (PMID 38526670, 2024). "The BRD4 inhibitor Pelabresib (CPI-0610) has shown synergistic anticancer effects, when combined with Ruxolitinib, the current standard of care treatment in myelofibrosis patients, in 84 myelofibrosis patients in a Phase II clinical trial." (PMID 38135679, 2023).
osteoarthritis (5 papers, 2019 to 2024). A noninflammatory degenerative joint disease occurring chiefly in older persons, characterized by degeneration of the articular cartilage, hypertrophy of bone at the margins and changes in the synovial membrane. "By administering inhibitors of BRD4 or Cbx4 into the joint cavity, we successfully suppressed the inflammatory response in osteoarthritis and reduced cartilage damage in rats." (PMID 39349832, 2024). "BRD4 worked as a vital pro-inflammation factor in inflammation-related diseases such as osteoarthritis and vascular inflammation." (PMID 33679744, 2021). "It has been proved that the BRD4-NF-κB signaling pathway has a great contribution to the development of gout arthritis, diabetic intervertebral disc degeneration, osteoarthritis, and rheumatoid arthritis." (PMID 33462181, 2021). "This study revealed the upregulation of Cbx4 and SUMOylated BRD4 in the synovial tissues of knee joints in patients with PTOA and in a rat model of osteoarthritis-induced ACLT." (PMID 39349832, 2024).
osteoporosis (5 papers, 2016 to 2025). A condition of reduced bone mass, with decreased cortical thickness and a decrease in the number and size of the trabeculae of cancellous bone (but normal chemical composition), resulting in increased fracture incidence. "Collective investigations convey a new epigenetic insight into acetyl histone reader BRD4 control of osteogenesis and adipogenesis in skeleton, and highlight the remedial effects of the BRD4 inhibitor on glucocorticoid-induced osteoporosis." (PMID 32575577, 2020). "Collective evidence conveys a new epigenetic insight into glucocorticoid-induced bone loss and marrow adipocyte overgrowth and highlights the remedial effect of BRD4 inhibitor to osteoporosis." (PMID 32575577, 2020). "Pharmacological inhibition of BRD4 is shown to inhibit osteoclast differentiation, preventing bone tissue from osteoporosis in ovariectomized mice." (PMID 32575577, 2020). "Targeting Brd4 by dBET6@PSLs could alleviate osteoporosis progression." (PMID 41115147, 2025). "Recently, we showed that NMP acts as a low affinity bromodomain inhibitor for BRD2, BRD3, BRD4, and BRDT and has potential for osteoporosis treatment." (PMID 27110299, 2016).
Pulmonary Diseases (5 papers, 2015 to 2025). "BRD4 is increasingly being recognized for its crucial involvement in modulating various physiological and pathological processes associated with pulmonary diseases." (PMID 41280641, 2025). "In this review, we will focus on findings implicating BET proteins, particularly BRD4, in the pathogenesis of these pulmonary diseases, the implications of BRD4 in disease progression, and the underlying mechanisms they control." (PMID 37686037, 2023). "With the accumulation of relevant research, BRD4 is also becoming a biological target for drug development for the treatment of airway inflammation and relevant lung diseases." (PMID 36721187, 2023). "Increasing evidence suggests the participation of BET proteins, particularly BRD4, in the development of pulmonary diseases." (PMID 37686037, 2023). "The following sections will discuss the novel functions of BRD4 in pulmonary diseases based on findings from in vitro assays and preclinical models." (PMID 37686037, 2023). "Emerging evidence highlights BRD4 as a potential therapeutic target in pulmonary diseases." (PMID 41280641, 2025). "However, the studies of the BRD4/AKT/SIRT3 signaling pathway in pulmonary diseases remains relatively limited." (PMID 41280641, 2025). "In this review, we provide a brief overview of the research on BET proteins with a focus on BRD4 in several major human lung diseases, the underlying molecular mechanisms, as well as findings of targeting BET proteins using pharmaceutical inhibitors in different lung diseases preclinically." (PMID 37686037, 2023). "It has been showed that BRD4 inhibitor JQ1 upregulated SIRT1 and alleviated inflammatory responses in a cellular model of lung disease." (PMID 32457617, 2020).
pulmonary hypertension (5 papers, 2023 to 2025). Increased pressure within the pulmonary circulation due to lung or heart disorder. "ZFC3H1 promotes the expression of BRD4 and HIF1a in PASMC, and its inhibition leads to the down-regulation of BRD4 and HIF1a and the reversal of the PAH phenotype in a murine model of pulmonary hypertension." (PMID 38132114, 2023).
rheumatoid arthritis (5 papers, 2020 to 2024). A chronic, systemic autoimmune disorder characterized by inflammation in the synovial membranes and articular surfaces. "For example, HOTTIP participates in acute gouty arthritis through miR-101-3p/BRD4 and is associated with rheumatoid arthritis." (PMID 38238652, 2024). "We show that both BRD2 and BRD4 control inflammatory cytokine production in NK cells isolated from healthy volunteers and from rheumatoid arthritis patients." (PMID 33717143, 2021).
type 2 diabetes (5 papers, 2017 to 2025). "ERK5 elicits inflammation, is increased in Type II diabetics, and plays a pathologic role in diabetic nephropathy, while BRD4 induces retinal inflammation and plays a role in retinal degeneration." (PMID 34456740, 2021). "Therefore, deficiency and inhibition of BRD4 may induce type 2 diabetes." (PMID 34336926, 2021). "Because eWAT and prWAT are linked to insulin resistance and type 2 diabetes, the reduced size of WAT from increased lipolysis triggered by Gdf3 reduction might account for the improved insulin sensitivity in Brd4-CKO mice." (PMID 33830083, 2021).
asthma (4 papers, 2015 to 2023). "In cat dander-induced asthma, Tian and colleagues further showed that BRD4 was also induced to complex with NF-κB/RelA in primary human hSAECs." (PMID 37686037, 2023). "BRD4 affects multiple cell types to promote asthma by modulating the secretion of proinflammatory and profibrotic mediators, cell differentiation, EMT, and imbalance of proliferation/apoptosis of ASMCs." (PMID 37686037, 2023). "The role of BRD4 in airway remodeling, another key feature of severe asthma, has gained much attention recently." (PMID 37686037, 2023). "The synthesis of BRD4-dependent BALF proteins were validated in humans with severe asthma." (PMID 35590254, 2022). "Our chromatin immunoprecipitation data show that there was a greater amount of enrichment of Brd4 at the IL6 and IL8 promoters at baseline in ASM cells from severe asthma compared with nonasthmatics subjects." (PMID 25697361, 2015).
COVID-19 (4 papers, 2020 to 2022). A disease caused by infection with severe acute respiratory syndrome coronavirus 2. "Their findings suggest an intimate relationship between COVID-19 and BRD4 and demonstrate that BET bromodomain inhibition can reduce cardiac stress and improve relaxation of the heart in the face of a cytokine storm triggered by SARS-CoV-2 infection." (PMID 34901955, 2022). "In COVID-19, BRD4, ubiquitous hubs commonly found in multiple tissues, is also expected to be drug targets for rescuing multiple organ injuries and dealing with inflammation." (PMID 33647885, 2021). "It should be noted that BRD2/BRD4 are potential drug targets of Envelope (E) protein, a structural proteins of COVID-19, which plays a central role in virus morphogenesis and assembly." (PMID 33082858, 2020). "The mechanism(s) by which BET inhibition ameliorates CS-induced DD remains a mystery, and we are left to assume that, in COVID-19 patients, BRD4 is activated upon phosphorylation to stimulate pathological gene expression that results in cardiac relaxation impairment." (PMID 34901955, 2022). "This two-strike model not only may explain the high comorbidity of COVID-19 and PTSD, but also opens vistas for novel interventions, including ARBs, ACEi, ASIC1a blockers, senolytics, furin inhibitors, BRD4 inhibitors and anti-glycolytic interventions." (PMID 34776871, 2021).
endometrial cancer (4 papers, 2020 to 2025). Primary or metastatic malignant neoplasm involving the endometrium (mucous membrane that lines the endometrial cavity). "We show that these focal deletions occur in the context of cyclin E1 amplification in breast, ovarian, and endometrial cancers, and serve to disrupt BRD4 regulatory regions and gene expression across isoforms." (PMID 40112818, 2025). "The enrichment for focal BRD4 deletions in breast, ovarian, and endometrial cancers was striking (p < 0.02 for all three tumor types, p < 0.005 for each alone; Fisher’s exact test)." (PMID 40112818, 2025). "Our data demonstrated that the antitumor effect of JQ1 to some extent was BRD4-dependent in endometrial cancer cells." (PMID 35902869, 2022). "We also sought to assess BRD4 protein expression in endometrial cancer using the Human Protein Atlas; this demonstrated “strong” BRD4 protein expression in 9/11 endometrial cancers." (PMID 32927694, 2020). "Univariate Cox regression analysis demonstrated that decreased mRNA expression of BRD4 was associated with decreased OS (HR = 2.034, 95% CI 1.009–4.102, p = 0.047) in the TCGA endometrial cancer cohort however this did not remain significant in a multivariate models." (PMID 32927694, 2020). "We similarly observed an increase in the mean CCNE1 copy number when considering only breast, ovarian, and endometrial cancers with and without a BRD4 focal deletion (7.1 vs. 4.1; p = 0.0002; Wilcoxon rank-sum test)." (PMID 40112818, 2025).
endotoxemia (4 papers, 2021 to 2022). "Brd4 is upregulated in colon tissue of mice with endotoxemia and promotes pyroptosis-related acute colon injury, however, the regulatory mechanism controlling Brd4 expression is unclear." (PMID 36539410, 2022). "In this paper, we mainly focused on affirming the connection between BRD4 and pyroptosis in endotoxemia colon." (PMID 33679744, 2021). "In the present study, we found that BRD4 expression was upregulated in colon of LPS-induced endotoxemia mice." (PMID 33679744, 2021). "In summary, we found the elevated expression of BRD4 in damaged endotoxemia colon with tight junction injury, and further used JQ1 as a BRD4 inhibitor to verify that the inflammatory pyroptosis was induced by BRD4 via NF κB signal in endotoxemia colon." (PMID 33679744, 2021). "Firstly, the BRD4 inhibitor JQ1 was used to effectively protect colon tight junction in endotoxemia." (PMID 33679744, 2021). "The protein expression of BRD4 in endotoxemia colons was powerfully inhibited by pretreatment with JQ1 (50 mg/kg, i.p.)." (PMID 33679744, 2021). "The active-formed gasdermins showed obvious upregulated trends in endotoxemia colon, which were effectively reversed by the pretreatment of BRD4 specific inhibitor JQ1." (PMID 33679744, 2021). "In this study, we firstly use the effective inhibitor JQ1 to explore how BRD4 functions in acute colon injury in endotoxemia." (PMID 33679744, 2021). "Here, through evaluating the mucous morphology and the expression of tight junction proteins such as occludin and ZO1, we found the upregulation of BRD4 in damaged colon with poor tight junction in an endotoxemia mouse model induced by lipopolysaccharides (LPS)." (PMID 33679744, 2021). "In this study, JQ1 pretreatment inactivated the NLRP3/ASC/caspase 1 inflammasome assembly, and eliminated the elevation of gasdermins, which indicated BRD4 might promoted pyroptosis to lead endotoxemia colon injury." (PMID 33679744, 2021). "Moreover, we discovered the rising gene and protein expression of an inflammasome complex containing NLRP3, ASC, and cleaved caspase 1 in endotoxemia colons compared to the control ones, which was also decreased by BRD4 inhibition." (PMID 33679744, 2021). "It was interesting that BRD4 protein level obviously increased in endotoxemia colons." (PMID 33679744, 2021). "In order to explore whether BRD4 also play a specific role in endotoxemia, western blot assay was used to detect the protein changes of BRD4 in endotoxemia colons compared to control colons." (PMID 33679744, 2021). "But it is still unclear whether there is a link between BRD4 and pyroptosis in endotoxemia colon." (PMID 33679744, 2021). "However, it is still unknown about the specific connection between BRD4 and inflammation-related pyroptosis in endotoxemia colon." (PMID 33679744, 2021). "Bromodomain-containing protein 4 (BRD4) was recently found to play a critical role in endotoxemia colon by regulating NLRP3/caspase-1/GSDMD-mediated pyroptosis, and BRD4 inhibition could prevent endotoxemia-induced colon damage through blocking inflammation-related pyroptosis." (PMID 36505474, 2022). "However, there is no study concerns about the effect of BRD4 inhibition on endotoxemia-related colon damage." (PMID 33679744, 2021).
esophageal squamous cell carcinoma (4 papers, 2021 to 2025). Esophageal squamous cell carcinoma (ESCC) is a type of esophageal carcinoma (EC) that can affect any part of the esophagus, but is usually located in the upper or middle third.
gouty arthritis (4 papers, 2020 to 2025). "Meanwhile, these effects were predominantly reversed through the pretreatment with BRD4 inhibitor JQ-1, suggesting its involvement of Caspase-1-dependent pyroptotic cell death in mechanisms of acute gouty arthritis." (PMID 33162822, 2020). "To address the role of BRD4 in acute gouty arthritis, we examined pyroptotic response in BRD4 knockdown (KD) THP-1 cells." (PMID 33162822, 2020). "Our study is the first research to reveal the role of BRD4 in MSU-induced NLRP3 inflammasome activation in acute gouty arthritis." (PMID 33162822, 2020). "For example, inhibition of BRD4 suppresses pyroptosis and alleviates acute gouty arthritis." (PMID 37035213, 2023). "Our current data demonstrated that BRD4 suppression could partially counteract the severity of pyroptotic death in acute gouty arthritis via the BRD4/NF-κB/NLRP3/GSDMD axis." (PMID 33162822, 2020). "Considering the connection between IL-1β and Caspase-1, flow cytometry was used to investigate whether BRD4 inhibitor have an impact on Caspase-1-dependent pyroptosis in animal model of gouty arthritis." (PMID 33162822, 2020). "It is firstly reported that BRD4 inhibition could contribute to the acute gouty arthritis therapy with the regulation of pyroptosis processing." (PMID 33162822, 2020).